EGFR (epidermal growth factor receptor)
Diseases named in the same sentence as EGFR in open-access papers (continued):
Sharing a sentence is not in itself a finding about the gene and the disease.
glioma (continued). "In the current study, we examine whether GOLPH3 affects the response of glioma cells to gefitinib, an EGFR selective inhibitor." (PMID 31094020, 2019). "Our previous study demonstrated that LRIG3 could modulate the proliferation, apoptosis, and invasion of glioma cells and functions as a tumor suppressor by attenuating the EGFR signaling pathway." (PMID 31245283, 2019). "EGFR is found to be amplified in gliomas in 40% of patients, often with structural rearrangement." (PMID 30991681, 2019). "As reported by other studies, EGFR amplification was more common in IDH-wildtype gliomas." (PMID 31623593, 2019). "The 3p14.1 and 11q23.3 loci are strongly associated with EGFR amplification negative gliomas, with a consistent albeit non-significant trend at 1p31.3 and 1q44, consistent with elevated upstream EGFR activation masking their functional effects." (PMID 29460007, 2018). "Additionally, a soluble form of the LRIG1 ectodomain can inhibit EGFR signaling in trans as well as suppress the proliferation of glioma cells in vitro and the growth of human glioma xenografts in vivo." (PMID 29391393, 2018). "BTK also appeared to be required for EGFR-induced NF-κB activation in glioma cells." (PMID 29561760, 2018). "To be able to investigate tumour heterogeneity with respect to oncogene expression, we applied padlock probe rolling circle amplification to indentify EGFR, MET and the whole-exon deletion splice variants of these oncogenes that play a role in, among others, glioma and NSCLC1,5,16,29–31." (PMID 29728634, 2018). "In addition to the integrated phenotypic and genotypic features of glioma, many genetic studies have found that common inherited variants near several genes (TERC, TERT, EGFR, CDKN2B, PHLDB1 and RTEL1) are associated with increased risk of adult glioma." (PMID 30462709, 2018). "Interestingly, in their cohort, SSTR2 was significantly overexpressed (p = 0.0001) in the 1p/19q-codeleted group when compared to the EGFR amplified high grade gliomas." (PMID 30193580, 2018). "Moreover, glioma stem cell division showed asymmetry in the distribution pattern of other key stem cell markers, such as Numb, EGFR and Nestin." (PMID 30510501, 2018). "Although we cannot exclude that other pathways may involve in DSE-mediated phenotypes, blocking EGFR/ErbB2 signaling by afatinib can inhibit DSE-induced malignant phenotypes in glioma cells." (PMID 29864158, 2018). "Binds to ErbB receptor and inhibits EGFR activity (glioma cell proliferation)." (PMID 30271342, 2018). "Mutations in EGFR were found to be the most commonly co-occurring change with SETD2 changes and were seen in 40% of the high grade gliomas in this cohort, similar to the frequency of EGFR mutations found in high grade gliomas overall." (PMID 30419952, 2018). "Multiple groups have used EGFR and EGFRvIII receptors in glioma as targets for therapy." (PMID 30366424, 2018). "This asymmetry in glioma CSCs is ensured by different distribution of the GFR (EGFR) molecules, transcription factors (e.g., Oct4, Sox2, etc.), membrane glycoproteins and proteoglycans (CD133, NG2) regulating stem cell properties and suppressing differentiation." (PMID 30510501, 2018). "Treating the U87 glioma cell line with EGFR-targeted diphtheria toxin (DT-EGF) induced cell death by autophagy, promoting the release of immunomodulatory factors like the high-mobility group box protein 1 (HMGB1), reducing the inflammatory response and inhibiting necrosis." (PMID 30486451, 2018). "Mechanistically, FoxM1/ADAM17 axis activated the EGFR/AKT/GSK3β signaling pathway and ADAM17/EGFR/GSK3β axis could maintain FoxM1 stability in glioma cells." (PMID 29700308, 2018).
glioma (continued). "We investigated 350 glioma patients for the expression of the key EMT factors SLUG and TWIST by immunohistochemistry and immunofluorescence related to morpho-genetic alterations such as EGFR-amplification, IDH-1 (R132H) mutation and 1p/19q LOH." (PMID 29844871, 2018). "The PPI network analysis indicated the top ranking genes are responsible for regulation of programmed cell death, protein metabolic process, apoptotic process, EGFR signaling pathway and signaling transduction, suggesting they may play pivotal roles in glioma." (PMID 29046615, 2017). "Second, we did not explore the association between EGFR gene polymorphisms and different subtypes of glioma such as astrocytoma, oligoastrocytoma and GBM due to the insufficient original data." (PMID 29156842, 2017). "It emphasizes the molecular classification for gliomas, such as isocitrate dehydrogenase (IDH) gene mutations, epidermal growth factor receptor (EGFR) status, methyl-guanine methyltransferase (MGMT) promoter methylation status, and chromosome 1p/19q codeletion." (PMID 29097933, 2017). "Furthermore, BTK inhibition suppresses the proliferation of glioma cells in vitro and in vivo, and abolishes the EGFR-induced NF-κB activation." (PMID 28946903, 2017). "However, the differences between Akt and MEK/ERK1/2 downstream of EGFR activation have remained less clear in glioma and GSCs." (PMID 28830458, 2017). "Next, we analyzed all gliomas patients in which EGFR mRNA was overexpressed by twofold (blue)." (PMID 29203859, 2017). "Gliomas may contain subpopulations of cells carrying mutually exclusive amplifications of oncogenes EGFR and PDGFRα." (PMID 28074274, 2017). "In glioma, EGF mainly promotes glioma cells proliferation through EGFR-MEK-ERK-ELK pathway." (PMID 29246166, 2017). "For low-grade glioma and anaplastic astrocytoma, The overexpression of EGFR may be a prominent event in the progression of gliomas with a poor prognosis." (PMID 28938685, 2017). "As their upregulation in glioma correlates with the upregulation of EGFR and EGFRvIII, the proteases might be an interesting target to examine closer." (PMID 28629170, 2017). "This resulted in abrogation of epidermal growth factor receptor pathway activation in glioma cells." (PMID 29029435, 2017). "Another factor, known to stimulate both proliferation and migration, is the epidermal growth factor (EGF); indeed, overexpression of its receptor (EGFR) is a feature which characterizes high-grade gliomas, with the highest expression level at the invasive niche." (PMID 29261132, 2017). "The effect of EGFR-targeted therapy has been extensively tested in preclinical human glioma models." (PMID 29069805, 2017). "EGFR activation or constitutive EGFR signaling induce ROS production in glioma cell lines." (PMID 28491867, 2017). "This was consistent with a previous study that EGFR amplification was frequently found in gliomas and could be used as a biomarker for the diagnosis of this cancer." (PMID 29190914, 2017). "Indeed, pharmacological agents blocking EGFR signaling combined with BRAFi inhibited orthotopic glioma xenografts and increased apoptosis, with resultant significant extension of animal survival." (PMID 29033690, 2017). "BTK is required for EGFR-induced NF-κB activation in glioma cells." (PMID 28946903, 2017). "In addition to this, a paracrine mechanism driven by EGFRvIII promotes tumor proliferation of EGFR-expressing human glioma cells and stem-like cells (GSCs) and thereby increases tumor heterogeneity and invasiveness." (PMID 28629170, 2017). "However inhibition of EGFR did enhance the chemo- and radio-sensitivity of both canine and human glioma CSCs, enabling this resistant, tumourigenic population of cells to be effectively targeted by conventional therapies." (PMID 29069805, 2017). "Other than SSTR2, EGFR was also highly expressed in glioma samples." (PMID 29029435, 2017). "The genetic alterations of EGFR pathway are the most common oncogenic drivers in glioma." (PMID 28946903, 2017).
glioma (continued). "Thus, this study provides clinical and mechanistic evidence demonstrating that H3K23ac/TRIM24 is critical for EGFR-driven tumorigenesis in human gliomas." (PMID 29129908, 2017). "In summarize, we demonstrated that AQP5 gene silencing could inhibit the proliferation, reduce the migration and promote the apoptosis of human glioma cells by suppressing EGFR/ERK/p38 MAPK signaling pathway." (PMID 28404978, 2017). "Indeed, ERK activity has been found to be highly elevated in glioma under EGFR amplification, while Akt activation is also frequent and has been shown to be important for neural cancer stemness." (PMID 28830458, 2017). "We show that ectopic expression of miR-135a in U87 glioma cells downregulates EGFR expression." (PMID 29268774, 2017). "Here, we show that both canine and human glioma cell lines contain a small population of cancer stem cells (CSCs), and by molecular profiling highlight the important role of the epidermal growth factor receptor (EGFR) pathway in canine CSCs." (PMID 29069805, 2017). "Glioma cells may over-express EGFR, which is a tyrosine kinase receptor, resulting in cell proliferation and invasion with downstream effects." (PMID 28404978, 2017). "In addition, increased integrin-b1/EGFR heteroassociation was detected in glioblastoma compared with low grade gliomas." (PMID 29246031, 2017). "EGFR signaling pathways are promising targets for therapeutic intervention in glioma." (PMID 29268774, 2017). "To understand why TRIM24 is important for EGFR/EGFRvIII-driven glioma tumorigenesis, we performed transcriptome analysis in LN229 parental (LN229/P) and LN229/EGFRvIII (LN229/vIII) GBM cells transfected with an empty vector or TRIM24 shRNAs (LN229/vIII/shT24-1 and LN229/vIII/shT24-2) using RNA-seq." (PMID 29129908, 2017). "Indeed, we found that forced expression of Kindlin-2 in glioma cells increased EGFR expression, while Kindlin-2 depletion decreased EGFR levels in glioma cells." (PMID 27713156, 2016). "We hypothesized that the Kindlin-2/β-catenin/YB-1 complex could regulate EGFR transcription in glioma." (PMID 27713156, 2016). "There is strong evidence that antagonism of EGFR leads to radiosensitization in high grade glioma." (PMID 27043632, 2016). "EGFR signaling in glioma cells regulates the expression of the angiogenic factor VEGF." (PMID 27385209, 2016). "Among the 166 RMPAhigh gliomas, 88 harbored focal amplification of EGFR, and 35 of these EGFR amplifications also harbored mutations in EGFR; an additional 7 RMPAhigh gliomas harbored EGFR mutations without detectable focal amplification." (PMID 27385209, 2016). "The EGFR signaling pathway also plays a critical role in glioma." (PMID 27713156, 2016). "Finally, we determined that Kindlin-2 formed a transcriptional complex with Y-box binding protein-1 (YB-1) and β-catenin that enhanced EGFR transcription and promoted glioma cell proliferation, migration, and invasion." (PMID 27713156, 2016). "However, we determined that ectopic expression of Kindlin-2 increased EGFR mRNA levels, which was significantly decreased in Kindlin-2 -depleted glioma cells, suggesting that Kindlin-2 regulated EGFR transcription." (PMID 27713156, 2016). "Thus, future studies of the functions of SNPs in EGFR are warranted in order to fully understand their effects on the prognosis of patient with glioma." (PMID 27437777, 2016). "In addition to NSCLC, the amplification of EGFR expression and signaling is a common feature in a variety of human cancers including prostate, gastric, ovarian, colorectal, renal, breast, glioma and head and neck cancers." (PMID 27057632, 2016).
glioma (continued). "Finally, Kindlin-2 formed a tripartite transcriptional complex with YB-1 and β-catenin, which bound to the EGFR promoter and enhanced EGFR transcription and glioma cell proliferation and motility." (PMID 27713156, 2016). "Anti-EGFR therapy with targeting MBs inhibited the growth rate of glioma in BALB/c nude mice." (PMID 25960704, 2015). "All these together indicate that PLCγ1 and EGFR might be involved in enhancing migration of glioma cells exposed to microglia and could potentially be acting as upstream regulators of the Pyk2 pathway." (PMID 26098895, 2015). "Especially, the epidermal growth factor receptor (EGFR) was involved in human tumors by regulating important cellular processes and several SNPs in the EGFR gene may be related to glioma risk." (PMID 25950430, 2015). "Furthermore, we examined the mechanisms by which ADAM17/EGFR/MAPK/ERK pathway contributed to miR-145-induced inhibition on glioma proliferation, invasion, and angiogenesis after transfection of miR-145." (PMID 25544346, 2015). "We previously reported that MET is crucially implicated in proliferation, survival and migration of (EGFR-negative) E98 glioma cells in vitro." (PMID 25862637, 2015). "We studied if combination genetic signature potentially stratifies lower-grade gliomas better than histology by investigating 214 lower-grade gliomas for IDH1/2 and TERTp mutations, 1p/19q codeletion and EGFR amplification as to their impact on prognostication." (PMID 26369702, 2015). "Among the 16 IDHwt-ET gliomas, nine cases harbored EGFR amplification as demonstrated by FISH." (PMID 26369702, 2015). "Loss of PTEN, such as the homozygous deletions observed in around 36% of gliomas, results in dramatic up-regulation of this pathway, and may be a major source of resistance to EGFR therapies." (PMID 25688333, 2015). "In consistent with these findings, CRNDE-expressing gliomas were found to have EGFR over-amplification, suggesting that, to a certain extent, CRNDE may be involved in the regulation of GSCs through the EGFR signaling pathway." (PMID 26230711, 2015). "Here we test the hypothesis that intrinsic resistance of glioma cells to BRAFV600E inhibitor PLX4720 is due to feedback activation of EGFR and its downstream signaling pathways." (PMID 26023796, 2015). "Presence of EGFR amplification and involvement of deep midline structures (including corpus callosum, thalamus, basal ganglia, ventricles and midbrain) in four cases suggested the possibility that these tumors are under-sampled high-grade gliomas." (PMID 26369702, 2015). "Evaluation of EGFR amplification and TERTp mutation in a background of wild-type IDH1/2 in lower-grade gliomas could help to identify aggressive tumors with seemingly low grade histology, facilitating a more precise prognostic estimation." (PMID 26369702, 2015). "A recent publication demonstrated that microglia stimulate migration of glioma cells through EGFR." (PMID 26098895, 2015). "Moreover, the involvement of EGFR in the motility of glioma cells was independently validated by our analyses with two clinically relevant EGFR inhibitors, lapatinib/Tykerb and gefitinib/Iressa." (PMID 26377974, 2015). "Furthermore, we analyzed the expression of EGF receptor (EGFR), which is expressed in immature astrocytes, is critical for astrocyte development, and is frequently overexpressed in high-grade glioma cells." (PMID 25623281, 2015). "Moreover, expression of phosphorylated-AKT (p-AKT) and EGFR, which are well-known oncogenes playing essential roles in control of glioma cell proliferation, were obviously decreased by miR-340." (PMID 25831237, 2015). "The present study showed that the combination of Nimotuzumab and rapamycin could enhance glioma cell death, in an EGFR independent manner." (PMID 25886314, 2015).
glioma (continued). "Detection of molecular glioma biomarkers such as MGMT promoter methylation, IDH1/IDH2 mutation, 1p/19q co-deletion, epidermal growth factor receptor (EGFR) amplification and EGFR variant III (EGFRvIII) expression in tumor tissue is increasingly being used in clinical care." (PMID 25720744, 2015). "Moreover, downregulation of EGFR and inhibition of phosphorylation of AKT indicated that miR-340 was able to suppress the aberrant EGFR signaling which is important in glioma progression." (PMID 25831237, 2015). "Immunoblots showed a high level of EGFR in these glioma cells." (PMID 25594013, 2014). "Therefore, the EGFR/PI3K/Akt/mTOR pathway is regarded as the most amenable pathway to pharmacologic intervention in glioma." (PMID 24418474, 2014). "Although EFEMP1's anti-cancer activity has most commonly been attributed to its anti-angiogenic effects, we showed for gliomas that EFEMP1's binding to EGFR accounts for its suppression of the intracranial tumorigenicity of glioma cells expressing high levels of EGFR." (PMID 25594013, 2014). "This is exemplified by the EGFR pathway’s contribution to radiation or chemo resistance in glioma." (PMID 24650032, 2014). "Using published mRNA signatures associated with EGFR activation, we demonstrate that G-CIMP+ tumors harbor decreased EGFR signaling using three independent datasets, including the Chinese Glioma Genome Atlas(CGGA; n=155), the REMBRANDT dataset (n=288), and The Cancer Genome Atlas (TCGA; n=406)." (PMID 25277177, 2014). "The epidermal growth factor receptor (EGFR) mutant of EGFRvIII is highly expressed in glioma cells, and the EGFRvIII-specific dendritic cell (DC)-induced tumor antigen-specific CD8+ cytotoxic T lymphocytes (CTLs) may hold promise in cancer immunotherapy." (PMID 24816916, 2014). "Having confirmed that a miR-566 inhibitor could deactivate the EGFR pathway and inhibit the proliferative and invasive behavior of glioma cells, we then demonstrated whether the functions of miR-566 were mainly through the EGFR pathway." (PMID 24650032, 2014). "We hypothesized that miR-566 could regulate the EGFR pathway and influence the sensitivity of glioma cells to anti-EGFR therapy." (PMID 24650032, 2014). "EGFR GCN heterogeneity is a well-established phenomenon in gliomas." (PMID 24940619, 2014). "In the EGFR-low glioma subset (N = 115), EFEMP1 data analysis showed a significant, unfavorable, patient prognosis, with HR = 1.7 and a 95% confidence interval = (1.1 – 2.7), while in the EGFR-high glioma subset (N = 51), the EFEMP1 data lacked any significant prognostic value." (PMID 25594013, 2014). "In the present study, we confirmed that miR-566 was upregulated in human glioma cells, and repressing miR-566 could inactivate the EGFR pathway largely by targeting VHL." (PMID 24650032, 2014). "Because miR-566 can regulate EGFR signaling, we wondered whether it could sensitize glioma to the effects of nimotuzumab in vitro and in vivo and its underlying mechanism." (PMID 24650032, 2014). "Compared to the established close association between EGFR activation and EGFR gene amplification and mutation, the amplification, rearrangement and mutation of PDGFRA gene is present only in a small fraction of gliomas." (PMID 24489888, 2014). "Given that ADAM17 enhances cell invasion and the degree of malignancy by activating EGFR in a variety of tumor cells, we propose that ADAM17 may have the same role as an oncogene in glioma, however, the underlying mechanism remains to be investigated." (PMID 25364437, 2014). "Furthermore, gain-of-function mutations in PI3KCA have been found in 15% of glioma samples and pre-clinical studies have shown that dual PI3KCA/mTOR inhibitors augment the antiproliferative effects of EGFR inhibition." (PMID 24716189, 2014).